FAAP24 (FA core complex associated protein 24)
Description:
Plays a role in DNA repair through recruitment of the FA core complex to damaged DNA. Regulates FANCD2 monoubiquitination upon DNA damage. Induces chromosomal instability as well as hypersensitivity to DNA cross-linking agents, when repressed. Targets FANCM/FAAP24 complex to the DNA, preferentially to single strand DNA.
Synonyms: C19orf40; FLJ46828; MGC32020
Tractability: No criterion of Open Targets' tractability assessment is met for any kind of drug.
Gene: Protein-coding gene on chromosome 19 (32,972,209 to 32,978,229, forward strand). Ensembl gene ENSG00000131944.
Subcellular location: Nucleus
Subcellular location (Human Protein Atlas): Nucleoplasm; Vesicles
Pathways (Reactome):
DNA Repair: Fanconi Anemia Pathway
Immune System: PKR-mediated signaling
Gene Ontology:
Molecular function: chromatin binding; protein binding
Biological process: interstrand cross-link repair
Cellular component: chromatin; FANCM-MHF complex; Fanconi anaemia nuclear complex; nucleoplasm; cytosol; nucleus
Genetic constraint (gnomAD): Loss-of-function variants: 19 observed, 20.86 expected, observed/expected ratio (o/e) 0.91, 90% interval 0.63 to 1.34. The upper end of that interval is the gene's LOEUF score, 1.34, which puts it in group 5 of 6, group 1 being the genes least tolerant of losing a copy. Missense variants: 224 observed, 267.56 expected, observed/expected ratio (o/e) 0.84, 90% interval 0.75 to 0.94. Synonymous variants: 109 observed, 110.58 expected, observed/expected ratio (o/e) 0.99, 90% interval 0.84 to 1.16.
Gene-disease validity (ClinGen):
ClinGen rates the evidence that FAAP24 causes each of these diseases.
lymphoproliferative syndrome (autosomal recessive): Disputed. A disorder characterized by proliferation of lymphocytes at various stages of differentiation.
Homologues: Orthologues: chimpanzee FAAP24 (98% identical), macaque FAAP24 (97% identical), guinea pig FAAP24 (88% identical), rabbit FAAP24 (87% identical), pig FAAP24 (83% identical), mouse Faap24 (81% identical), rat Faap24 (80% identical), dog FAAP24 (73% identical), tropical clawed frog faap24 (57% identical), zebrafish faap24 (52% identical).
Diseases named in the same sentence as FAAP24 in open-access papers:
FAAP24 is named in the same sentence as 15 diseases in open-access papers, as found by Europe PMC text mining. Sharing a sentence is not in itself a finding about the gene and the disease. The quoted sentences say what the papers report.
Fanconi anemia (9 papers, 2018 to 2025). Fanconi anemia (FA) is a hereditary DNA repair disorder characterized by progressive pancytopenia with bone marrow failure, variable congenital malformations and predisposition to develop hematological or solid tumors. "FAAP24 is associated with the recruitment of the Fanconi anemia complex and the regulation of ATR-CHK1 checkpoint signaling." (PMID 39718835, 2024). "The Fanconi anemia DNA repair pathway, in which FAAP24 involves, has recently been intensively studied for its contribution to anticancer drug resistance." (PMID 37328842, 2023). "As a core member of the FA complex, in the Fanconi anemia pathway, FAAP24 plays an important role in DNA damage repair." (PMID 37328842, 2023). "Pathway analyses with the KEGG and REAC databases revealed a significant enrichment of the Fanconi anemia (FA) repair pathway, with notable genes such as BRIP1 (FANCJ), FANCI, FANCA, SLX4 (FANCP), UBE2T (FANCT), and C19orf40 (FAAP24)." (PMID 38896450, 2024).
breast carcinoma (3 papers, 2021 to 2023). "Loss of FAAP24 appeared in two distinct lineages in patient KTN102 and was associated with worse progression-free survival (PFS) in TCGA breast cancer data." (PMID 33622385, 2021). "The results showed that almost all cancers expressed higher FAAP24 than normal tissues, including BLCA (bladder urothelial carcinoma), BRAC (breast cancer), and CESC (cervical cancer)." (PMID 37328842, 2023). "The FA genes we identified as DEGs; CENPX, FAAP24, FANCD2, FANCI, UBE2T and FANCA are all overexpressed in breast cancer." (PMID 33662042, 2021).
anemia (2 papers, 2013 to 2024). A reduction in the number of red blood cells, the amount of hemoglobin, and/or the volume of packed red blood cells. "To understand how ICL is specifically recognized by the Fanconi anemia proteins FANCM and FAAP24, we determined the structure of the HhH domain of FAAP24." (PMID 23661679, 2013).
Infertility (1 paper, 2025). "A patient-derived mutation truncating the C-terminal HhH domain (p.Arg1931∗; rs144567652) associated with cancer predisposition and infertility showed similar defects, and is consistent with previous observations that both the C-terminal region and FAAP24 are essential for FANCM function." (PMID 40447800, 2025).
leukemia (1 paper, 2023). A malignant (clonal) hematologic disorder, involving hematopoietic stem cells and characterized by the presence of primitive or atypical myeloid or lymphoid cells in the bone marrow and the blood. "All these factors lead to the promotion of leukemia progression, which explains the poor prognosis of high FAAP24 expression in AML in our study." (PMID 37328842, 2023).
cancer (4 papers, 2018 to 2025). A tumor composed of atypical neoplastic, often pleomorphic cells that invade other tissues. "We further analysed the association between FAAP24 and OS across cancers using GEPIA2, and FAAP24 expression was significantly associated with survival in patients with six cancers." (PMID 37328842, 2023). "Deficiency of FAAP24 causes a cancer-prone recessive genetic disorder characterized by congenital abnormalities, bone marrow failure, and cancer susceptibility." (PMID 37328842, 2023). "Gene set enrichment analysis revealed that FAAP24 is implicated in pathways involved in DNA damage repair, the cell cycle and cancer." (PMID 37328842, 2023). "In this study, we examined the expression and prognostic value of FAAP24 across cancers using data from TCGA, TARGET, GTEx, and GEPIA2." (PMID 37328842, 2023). "Through an analysis of the public databases, we investigated FAAP24 expression differences across cancer types." (PMID 37328842, 2023). "The role of genetic and epigenetic changes in regulating cancer development and immune tolerance must be further explored, as well as the protein-protein interactions of FAAP24." (PMID 37328842, 2023). "Therefore, functional research on FAAP24 has also been extended to other cancers, including human clone cancer." (PMID 37328842, 2023). "The results showed that higher FAAP24 expression in AML strongly correlated with a stronger recruitment of MDSCs, TH2 cells and Treg cells but was negatively related to the process of killing cancer cells and priming of immune response." (PMID 37328842, 2023).
tumor (4 papers, 2016 to 2024). "Moreover, we also explored the correlation between FAAP24 and the enrichment scores of the tumor pathway from the hallmark gene set." (PMID 37328842, 2023). "Our study aimed to investigate the prognostic value of FAAP24 in AML, its relationship with tumor-infiltrating immune cells, and its associated pathways." (PMID 37328842, 2023). "Components of the immune microenvironment using xCell indicate that FAAP24 shapes an immunosuppressive tumor microenvironment (TME) in AML, which helps to promote AML progression." (PMID 37328842, 2023). "Further exploration of the strategies of tumor immune escape and the regulatory factors of M2 macrophages that are related to FAAP24 in AML would provide immunologic insights into novel treatments." (PMID 37328842, 2023). "Meanwhile, the high expression of FAAP24 is positively related to M2 macrophages, which are immunosuppressive and promote tumor progression by facilitating angiogenesis and tissue phagocytosis." (PMID 37328842, 2023). "Interestingly, previous studies implicated various FA complex proteins, such as FANCM, MHF1, FAAP20 and FAAP24, in tumor cell survival after DNA damage." (PMID 26625197, 2016). "To further explore the functional network and pathogenetic mechanism related to FAAP24 in AML, we investigated its regulatory function in tumor immunity and its interaction with m6A RNA methylation and cuproptosis in AML." (PMID 37328842, 2023). "Additionally, we found support for the SL interaction between LIG1 and PARP1 and EME1 and PARP1 by analyzing the coexpression of LIG1, EME1, or FAAP24 and PARP1 in relation to the tumor, node, metastasis (TNM) stage of PCa samples (P value for LIG1-PARP1 < 0.001; P value for EME1-PARP1 < 0.05)." (PMID 39718835, 2024).
FAAP24 also shares sentences with these, for which no sentence is quoted: Alpha-thalassemia (1 paper); bladder urothelial carcinoma (1); cervical cancer (1); Diamond-Blackfan anemia (1); glioma (1); lung adenocarcinoma (1); microcytic anemia (1); pancreatic adenocarcinoma (1).